ARL2-SNX15 (ARL2-SNX15 readthrough (NMD candidate))
Gene: Protein-coding gene on chromosome 11 (65,014,182 to 65,040,570, forward strand). Ensembl gene ENSG00000273003.
Genetic constraint (gnomAD): Missense variants: 127 observed, 143.02 expected, observed/expected ratio (o/e) 0.89, 90% interval 0.77 to 1.03. Synonymous variants: 67 observed, 58.15 expected, observed/expected ratio (o/e) 1.15, 90% interval 0.94 to 1.41.